UNC50 (unc-50 inner nuclear membrane RNA binding protein)
Description:
Involved in the cell surface expression of neuronal nicotinic receptors (By similarity). Binds RNA (By similarity).
Synonyms: PDLs22; UNCL; HSD23; URP; GMH1
Tractability: Antibody: UniProt predicts a signal peptide or a membrane-spanning region. PROTAC: ubiquitination databases record sites on it.
Gene: Protein-coding gene on chromosome 2 (98,608,434 to 98,618,515, forward strand). Ensembl gene ENSG00000115446.
Subcellular location: Nucleus inner membrane; Golgi apparatus membrane
Gene Ontology:
Molecular function: protein binding; RNA binding
Biological process: protein localization to cell surface
Cellular component: Golgi membrane; nuclear inner membrane; Golgi apparatus
Genetic constraint (gnomAD): Loss-of-function variants: 24 observed, 33.39 expected, observed/expected ratio (o/e) 0.72, 90% interval 0.52 to 1.01. The upper end of that interval is the gene's LOEUF score, 1.01, which puts it in group 4 of 6, group 1 being the genes least tolerant of losing a copy. Missense variants: 245 observed, 319.27 expected, observed/expected ratio (o/e) 0.77, 90% interval 0.69 to 0.85. Synonymous variants: 118 observed, 121.64 expected, observed/expected ratio (o/e) 0.97, 90% interval 0.83 to 1.13.
Homologues: Orthologues: chimpanzee UNC50 (100% identical), dog UNC50 (99% identical), macaque UNC50 (99% identical), pig UNC50 (98% identical), guinea pig UNC50 (97% identical), rat Unc50 (96% identical), mouse Unc50 (96% identical), tropical clawed frog unc50 (84% identical), zebrafish unc50 (80% identical), Drosophila melanogaster Unc50 (53% identical), Caenorhabditis elegans unc-50 (47% identical).
Diseases named in the same sentence as UNC50 in open-access papers:
UNC50 is named in the same sentence as 9 diseases in open-access papers, as found by Europe PMC text mining. Sharing a sentence is not in itself a finding about the gene and the disease. The quoted sentences say what the papers report.
arthrogryposis (3 papers, 2018 to 2025). A rare, non-progressive congenital disorder characterized by multiple joint contractures which are present at birth. "A mutation in the human gene UNC50 was recently associated with arthrogryposis, a severe fetal disease that can be caused by impairment of neurotransmission at the NMJ." (PMID 30407909, 2018). "The clinical findings in family 2 expand the phenotypic spectrum of UNC50-related disorders beyond arthrogryposis." (PMID 40219868, 2025).
hepatocellular carcinoma (2 papers, 2015 to 2020). A malignant tumor that arises from hepatocytes. "We investigated the relation between UNC50 and human hepatocellular carcinoma (HCC) and the potential mechanisms underlying HCC development." (PMID 25738771, 2015).
arthrogryposis multiplex congenita (1 paper, 2025). Arthrogryposis multiplex congenita (AMC) is a group of disorders characterized by congenital limb contractures. "Previously, a biallelic loss-of-function variant in UNC50 was reported in an individual with lethal arthrogryposis multiplex congenita." (PMID 40219868, 2025). "In a previously reported individual with a clinical presentation of arthrogryposis multiplex congenita (AMC), a homozygous frameshift deletion in the last exon of UNC50, c.750_751del p.(Cys251PhefsTer4), was identified." (PMID 40219868, 2025).
cancer (1 paper, 2015). A tumor composed of atypical neoplastic, often pleomorphic cells that invade other tissues. "In agreement with this, western blotting revealed that UNC50 was detectable in eleven of 12 cancer tissues and in only six of 12 non-cancerous tissues." (PMID 25738771, 2015).
neuromuscular disease (1 paper, 2025). "To conclude, this study describes two unrelated families of Indian origin with multiple affected subjects with severe and early-onset neuromuscular disease associated with biallelic variants in UNC50." (PMID 40219868, 2025).
tumor (1 paper, 2015). "This study relates the novel Golgi apparatus membrane protein UNC50 to an important tumor-promoting pathway that involves EGF." (PMID 25738771, 2015).
UNC50 also shares sentences with these, for which no sentence is quoted: epilepsy (1 paper); infection (1); neurodevelopmental disorder (1).